SATB2 (SATB homeobox 2)
Diseases named in the same sentence as SATB2 in open-access papers (continued):
Sharing a sentence is not in itself a finding about the gene and the disease.
tumor (continued). "Using qRT-PCR, we confirmed that SATB2, HDAC9, NAP1L2 expression was down-regulated in the tumor group." (PMID 38212708, 2024). "Among them, PHF19, AURKA, CHAF1B and AURKB were up-regulated in the tumor group, NAP1L2, TONSL, SATB2 and HDAC9 were down-regulated in the tumor group." (PMID 38212708, 2024). "The analysis of showed that PHF19, AURKA, CHAF1B and AURKB were up-regulated in the tumor group, NAP1L2, TONSL, SATB2 and HDAC9 were down-regulated in the tumor group." (PMID 38212708, 2024). "The mean methylation of CpGs in two genes is hypomethylated in normal and hypermethylated at the terminal tumor regions (USP44 and SATB2); the opposite is true for three other genes (KRBA1, ANKS4B, and KDM8)." (PMID 37120552, 2023). "In this study, it was found that hsa-miR-31-5p was significantly upregulated in HExo and bound to protein 2 by targeting a specific AT-Rich sequence (SATB2), and activation of the MEK/ERK pathway promotes tumor progression." (PMID 36635678, 2023). "Immunohistochemistry showed that the tumor cells were diffusely positive for TLE-1 and vimentin and focally positive for epithelial membrane antigen, AE1/3, Cam5.2, SATB2, and CD34 (all in less than 10% tumor cells)." (PMID 35125107, 2022). "In immunohistochemistry, expression of FGF23 was shown in the cytoplasm of the osteoblast-like tumor cells, CD56 was diffusely positive on the cell membrane of the tumor cells and SATB2 was diffusely positive on the tumor cells." (PMID 36686800, 2022). "By IHC, the tumor cells were diffusely positive for TLE-1 and vimentin and focally positive for epithelial membrane antigen, AE1/3, Cam5.2, SATB2, and CD34 (all in less than 10% tumor cells)." (PMID 35125107, 2022). "Diagnosis of gastrointestinal tract (GIT) tumours requires a different set of biomarkers, the most useful of which include CK20, CDX2, and most recently SATB2." (PMID 35027072, 2022). "We observed significant correlations between the expression levels of the core DEGs SATB-2, ORP-1, MYB, and CDX-2 and tumor immune cell infiltration represented by the expression of B cell, CD4+ T cell, CD8+ T cell, and macrophage markers in TCGA." (PMID 33632198, 2021). "SATB-2, ORP-1, MYB, and CDX-2 were related to cetuximab sensitivity as well as enhanced tumor immune cell infiltration in patients with CRC." (PMID 33632198, 2021). "In subsequent multivariate analyses incorporating all prognostic factors, SATB2 retained its prognostic relevance in both UICC stage III carcinomas and dissociative cancers with a high tumour budding activity." (PMID 34944797, 2021). "Here, we show that the Special AT‐rich Binding Protein‐2 (SATB2), one of crucial NMPs, recruits histone acetyltransferase CBP to promote the FOXM1‐mediated cell proliferation and tumor growth of GBM." (PMID 33124191, 2020). "We further identified CBP as a binding partner of SATB2 in activating FOXM1 expression to promote GSC proliferation and GBM tumor growth." (PMID 33124191, 2020). "Tumor-suppressive miR-34c was often downregulated in various types of tumor cells and regulated EMT through direct binding with SOX9, SATB2, MAP3K2, and DANCR mRNA." (PMID 32252322, 2020). "The expression of relevant molecular biomarkers of both tumor types, analyzed in all PDXs, was also faithfully mirrored by PDX, in particular SATB2 and PGP in OS PDX, CD99 and caveolin 1 in EW PDX." (PMID 31434953, 2019). "To investigate the roles of SATB2 in tumor cell growth and survival, we treated HCT116 cells with 2 different shRNAs specific for SATB2 (shSATB2-1, shSATB2-2)." (PMID 29254139, 2017). "miR-31 also regulates the expression of several target-suppressive or oncogenic genes, such as ARID1A, SATB2, EMSY, and ABCB9, to affect tumorigenesis and tumor progression and prognosis." (PMID 27793031, 2016). "In this study, we demonstrated that miR-182 acts as a tumor growth- and metastasis-promoter in human CRC through repression of SATB2." (PMID 24884732, 2014).
tumor (continued). "We found that the average levels of both SATB2 mRNA and protein were significantly lower in tumor specimens than in matched non-involved colon tissues." (PMID 40076993, 2025). "The IHC results revealed that the positive SATB2 staining rates for the 62 primary CRC tumor and adjacent normal tissues were 95.16% (59/62) and 98.39% (61/62), respectively." (PMID 40636538, 2025). "Immunohistochemical (IHC) study of the SATB2 protein localization and level included sections of tumor and matched non-involved colon tissues of 104 CRC patients." (PMID 40076993, 2025). "In our case, the tumor was positive for CDX2, CK20, and SATB2." (PMID 41328080, 2025). "Forty-six (69.7%) CRC tissue specimens showed decreased relative SATB2 mRNA levels (tumor vs. matched non-involved colorectal mucosa), while 20 (30.3%) showed increased levels of SATB2 transcripts." (PMID 40076993, 2025). "Although a negative correlation was found between the hypermethylation of SATB2 and its mRNA expression, this did not mean that the downregulated expression of SATB2 in CRC tumor tissue was caused entirely by hepermethylation." (PMID 40636538, 2025). "The expression of CDX2 and SATB2 was detected in variable proportions of tumor cell nuclei, while stromal cells were negative for both." (PMID 39998677, 2025). "In our study, we also established a xenograft model of ESCC in BALB/C-nu/nu nude mice and found that stable low expression of SATB2 inhibits the activity of the Wnt/β-catenin signaling pathway, thus inhibiting the EMT phenotype and radioresistance of the tumor tissue, and increases apoptosis." (PMID 40078194, 2025). "Immunohistochemical (IHC) staining revealed that the tumor cells were diffusely positive for SOX11 but negative for SATB2, CD56, S100, and TLE1." (PMID 40791569, 2025). "Given the established fact that SATB1 is upregulated in tumor tissues and cell lines derived from aggressive adenocarcinomas, the increased expression of SATB1 in 3D spheroids and the reciprocal expression to SATB2 corroborates the trend." (PMID 40689929, 2025). "Both tumor patterns were immunohistologically positive for CK20, CDX2, and CEA with predominantly equal intensities in the cells of the CC and CV components, respectively, whereas SATB2 was significantly reduced in the clear cells." (PMID 39039246, 2024). "Tumor cells expressed Ki-67 at approximately 60%, while SATB2, H3.3G34 W, WT1,and p63 exhibited negative expression." (PMID 38903727, 2024). "We also demonstrate that SATB2 is not expressed in normal PrECs, but it is highly expressed in CSCs, cancer cells, and primary tumor tissues." (PMID 38891096, 2024). "The tumor shows the positive expression of immunomarkers Smooth Muscle Actin, Vimentin, and Beta-catenin, while SATB2 is typically negative." (PMID 38378640, 2024). "We performed further an immunohistochemical examination, revealing that the tumor area was positive for vimentin and SATB2, while CK5/6 and SMA were negative." (PMID 39568569, 2024). "The tumor cells expressed SATB2, Bcl-2, TLE1, SMARCB1, but not CK, EMA, CD34, SMA, Desmin, S-100, CD99, STAT6, MyoD1, Myogenin, and Ki-67 LI is about 10%." (PMID 37361584, 2023). "Immunohistochemical staining demonstrated that tumor cells were positive for special AT-rich sequence-binding protein 2 (SATB2), Bcl-2, vimentin, and CD34, but negative for S-100 protein, epithelial membrane antigen (EMA), and smooth muscle actin (SMA)." (PMID 35363174, 2022). "For instance, a rectal biopsy with submucosal location of a poorly differentiated tumour was diagnosed as metastatic prostatic adenocarcinoma as the tumour cells were negative for SATB2 but positive for PSA and Alpha Methyacyl CoA racemase (AMACR)." (PMID 36200017, 2022). "The expression levels of RHOA, SATB2, and WAVE3 were all downregulated after 48 hours of GBK treatment, indicating that the tumor suppression effect exerted by GBK may be related to invasion/metastasis-associated signaling pathways." (PMID 36313626, 2022).
tumor (continued). "Our study identifies, for the first time, SATB2 and GATA3 expression as features of Hyams’ grades 1–3 ONBs, expands the spectrum of SATB2 and GATA3-positive neoplasms, and suggests that Hyams’ grade 4 ONBs are not only clinically but also biologically different from low graded ONBs." (PMID 35522392, 2022). "Compared to SATB2-high neoplasms, SATB2-low/absent CRCs were significantly increased in CRCs with high (Bd3) tumour budding activity and in poorly differentiated carcinomas according to the WHO grade (p < 0.001, respectively)." (PMID 34944797, 2021). "Exosomal miR-31-5p was found to directly target Special AT-Rich Sequence-Binding Protein 2 (SATB2)-revered epithelial mesenchymal transition and significantly increase activation of MEK/ERK signaling, thereby contributing to tumor progression both in vitro and in vivo." (PMID 34074322, 2021). "Only the number of positive tumour cells (regardless of staining pattern or intensity) were used to form the SATB2 expression groups." (PMID 34944797, 2021). "Further, hypoxic tumor-derived exosomal miR-31-5p triggers LUAD metastases through negative modulation of SATB2-reversed EMT as well as activation of the MEK/ERK pathway." (PMID 34925645, 2021). "This experimental approach could be used to try to identify pools/genes that can accelerate (e.g. SATB2) or delay (e.g. CBX3) tumor onset." (PMID 33527896, 2021). "Most CRCs showed a diffuse SATB2 expression (61%, n = 639), a heterogeneous staining was noted for 340 cancers (33%), 60 tumours (6%) showed a complete absence of SATB2." (PMID 34944797, 2021). "As FOXM1 is an oncogenic regulator that promotes GSC proliferation and expression of the stem cell marker SOX2, and SATB2 regulates FOXM1 expression, we next explored whether FOXM1 mediates the effects of SATB2 on GSC proliferation and tumor growth." (PMID 33124191, 2020). "Expression of SATB2 was observed in 3 of 11 (27%) duodenal, 9 of 45 (20%) jejunal and 8 of 44 (18%) ileal cases, without statistically significant differences by tumor site (p = 0.797)." (PMID 33228145, 2020). "Furthermore, SATB2 silencing inhibited EMT and their positive regulators, and tumour growth, and suppressed the expression of stem cell markers, pluripotency maintaining factors, cell cycle and cell survival genes, and TCF/LEF targets." (PMID 32885593, 2020). "We and others have demonstrated that human normal epithelial cells of several organs do not express SATB2 gene; however, it is highly expressed in cancer cell lines, CSCs and primary tumours of colon, liver, breast and pancreas." (PMID 32885593, 2020). "Therefore, we investigated the potential role of SATB2 in regulating GSC properties and GBM tumor growth, and found that SATB2 augmented GSC proliferation by recruiting histone acetyltransferase CBP to promote FOXM1 expression in GSCs." (PMID 33124191, 2020). "On the other hand, in some studies SATB1′s expression lacked a prognostic value or was a prognostic factor only in SATB2-negative tumours." (PMID 31450715, 2019). "Research in the mechanism of miR-31 found that it could target genes such as ARID1A, SATB2, ARID1A, HuR, BAP1, EZH2, and RASA1, and it could further activate oncogenes and promote tumor cell proliferation, migration and invasive capability in vitro." (PMID 28404921, 2017). "In addition, we identified that SATB2 can bind to DNMT3A and upregulate its protein expression, thereby indirectly affecting tumor growth and miR-449a and miR-34a expression via DNA methylation." (PMID 29254139, 2017). "SATB2 expression was assessable in 107/108 (99.1%) PB-type primary tumours, and denoted as positive in 3 (2.8%) cases and negative in 104 (97.2%) cases." (PMID 25323550, 2014). "SATB1 expression was positive in 2 and negative in 1 of the 3 cases with SATB2-positive PB-type tumours." (PMID 25323550, 2014). "In the group of I-type tumours, where SATB2 expression was more frequent (8/61), no prognostic effect was seen." (PMID 25323550, 2014).
tumor (continued). "Among 61/65 (93.8%) assessable I-type primary tumours SATB2 was positive in 8 (13.1%), and negative in 53 (86.9%) cases." (PMID 25323550, 2014). "One, more simplistic, explanation for this observation could be that the beneficial prognostic value of SATB2, being expressed in the majority of CRC overrules the potential tumour-promoting effects of SATB1." (PMID 22935204, 2012). "Immunohistochemical expression of SATB1 and beta-catenin was assessed in tissue microarrays with tumours from 529 incident CRC cases in the prospective population-based Malmö Diet and Cancer Study, previously analysed for SATB2 expression and MSI screening status." (PMID 22935204, 2012). "Therefore, further studies are needed to clarify the mechanisms by which SATB2 is involved in the development and progression of LSCC as a tumor suppressor and its exact role in the regulation of chromosome instability in LSCC." (PMID 22815795, 2012). "SATB2 might involve in the development and progression of LSCC as a tumor suppressor, and thereby may be a valuable prognostic marker for LSCC patients." (PMID 22815795, 2012). "Lower or negative SATB2 expression was significantly correlated with advanced clinical staging, histological grade and tumor recurrence." (PMID 22815795, 2012). "The aim of this study was to compare SATB2 gene expression in tumor and matched non-involved colorectal tissues obtained from CRC patients, and to investigate its association with clinicopathological and demographic parameters, as well as patients’ overall survival." (PMID 40076993, 2025). "As the explants used in the current study represent a sample of quasi-resistant tumours (non-responders) it would be interesting to assess SATB2 and CD80 expression in tissue from LNG responders to determine their clinical applicability as biomarkers of LNG response." (PMID 38635728, 2024). "It should be mentioned that non-CRC with intestinal differentiation or of mucinous type were recognised to express high rates of CDX2 and/or CK20 opposed to SATB2 that frequently addressed negative expression in those tumours even if they show intestinal differentiation." (PMID 36819801, 2022). "In fact, these neoplasms are thought to originate from neuroepithelial (neuroectodermal) olfactory cells that are normally found in the upper part of the nasal cavity, in which SATB2 has not been found to be physiologically expressed." (PMID 35522392, 2022). "In UICC stage III tumours, SATB2-low/absent showed significantly shortened survival characteristics (OS: 70.3 months vs. 84.4 months, p = 0.025; DSS: 74.5 months vs. 91 months, p = 0.012; DFS: 62.1 months vs. 81.2 months; p = 0.004) in all survival comparisons." (PMID 34944797, 2021). "Given the lack of proliferation changes, we next asked whether SATB2’s aggressive tumor phenotype and internal tumors might be explained by an increase in tumor migration and/or invasion." (PMID 33527896, 2021). "As SATB2/CBP plays critical roles in promoting GSC proliferation and GBM growth, we next explore whether pharmacologic inhibition of CBP activity by a small molecule inhibitor named C646 could impact GSC‐driven tumor growth." (PMID 33124191, 2020). "Furthermore, reduced tumor volumes and weights, fewer Ki67-positive cells and more TUNEL-positive cells were also observed in the xenografted tumors of SATB2-knockdown cells, suggesting that the growth arrest induced by miR-449a is similar with SATB2." (PMID 29254139, 2017). "Additionally, the observed absence of decreased SATB2 levels upon SATB1 knockdown in cells from another tumor entity further substantiates the notion of SATB2 reduction as a specific effect downstream of SATB1." (PMID 28049521, 2017). "However, the tumor initiating, promoting and metastatic roles of SATB2 in colorectal carcinogenesis have never been examined." (PMID 28887549, 2017).
tumor (continued). "Thus, SATB2 functions as a critical mediator in both the negative feedback loop that maintains low levels of miR-449a and miR-34a and the suppression of tumor growth and survival." (PMID 29254139, 2017). "However, the tumor promoting and metastatic roles SATB2 in pancreatic carcinogenesis have never been examined." (PMID 27472393, 2016). "In the complete evaluated cohort, 152 out of 527 (28.8%) tumours were negative for SATB2." (PMID 22333599, 2012). "Moreover, SATB1 is not only expressed in tumour cells, but also in stromal lymphocytes, and, importantly, the prognostic impact was evident even at low levels of expression, not least in the subgroup of SATB2 negative tumours." (PMID 22935204, 2012). "Furthermore, while not prognostic in the full cohort, SATB1 expression was found to be a factor of poor prognosis in SATB2 negative tumours." (PMID 22935204, 2012). "Furthermore, while not prognostic in unstratified analysis, SATB1 expression is shown to be a factor of poor prognosis in SATB2 negative tumours." (PMID 22935204, 2012). "In conclusion, this study showed the first evidences of the expression and clinical significance of SATB2 in LSCC, suggesting that SATB2 might involve in the development and progression of LSCC as a tumor suppressor, and thereby may serve as a valuable prognostic marker for LSCC patients." (PMID 22815795, 2012). "However, it remains unclear whether SATB2 is differently expressed within purely morphological (adenocarcinoma NOS vs. specific CRC subtypes, tumour budding subcategories (Bd1/2/3), WHO low- vs. high-grade carcinomas), immunohistochemical (CDX2 expression) and pTNM/UICC stage subgroups." (PMID 34944797, 2021). "Furthermore, SATB2 closely related gene SATB1 did not affect tumor development." (PMID 33527896, 2021). "Furthermore, SATB1 expression is a factor of poor prognosis in SATB2 negative tumours." (PMID 22935204, 2012). "Notably, none of the SATB2 negative tumours displayed high SATB1 staining." (PMID 22935204, 2012). "The tumor was positive for CD99, SATB2, TLE1, cyclin D1, and focal FLI1, while negative for EMA, S100, desmin, calponin, and SOX10." (PMID 41869091, 2026). "Specifically, tumor cells expressed CK20, CDX2, CK7, and SATB2, while they were negative for PAX8 and WT1." (PMID 40205657, 2025). "Immunohistochemical results showed that the tumor cells expressed Vimentin, SMA, Bcl-2, CD56, CD34, CD31, Ki-67, ERG, RB, INI-1, and SATB2, but were negative for SSTR2 and CK." (PMID 40406261, 2025). "The tumor cells were negative for special AT-rich sequence-binding protein 2 (SATB2) and caudal type homeobox 2 (CDX-2), which rules out the possibility that the tumor cells originate from the digestive tract (stomach, small intestine, colon, etc.)." (PMID 40013097, 2025). "The non-epithelial characteristics of this tumor were demonstrated by the immunohistochemical results, which were negative for AE1/3 and CK5/6 and positive for vimentin and SATB2." (PMID 39568569, 2024). "Immunohistochemical staining was carried out and showed positive staining for CK20, CDX2, and SATB2 and negative staining for CK7, indicating the recurrent tumor’s primary colon origin." (PMID 37280577, 2023). "Immunophenotypically, the tumor was positive for Cytokeratins Oscar and 7, GATA3, GCDFP, HER2, and an androgen receptor but negative for CK20, S100, p40, Melan A, CDX2, TTF1, ER, SATB2, DOG1, synaptophysin, and chromogranin." (PMID 37886914, 2023). "Immunohistochemical stains showed the tumor cells to be positive for CDX2, CK20, and SATB2 and negative for p63, GATA3, CK7, and Uroplakin II, indicating the colorectal origin of the tumor." (PMID 35178262, 2022). "Overexpression of SNAI2 resulted in a significant acceleration of tumor onset compared to the EGFP negative control, albeit milder than SATB2 (MCR:SNAI2 median onset 18 weeks vs 12 weeks for MCR:SATB2)." (PMID 33527896, 2021).